GSK3B (glycogen synthase kinase 3 beta)
Diseases named in the same sentence as GSK3B in open-access papers (continued):
Sharing a sentence is not in itself a finding about the gene and the disease.
breast cancer (continued). "GSK3-β is a known oncotherapeutic target: inhibition GSK3-β with small compounds promotes cell death in different types of cells, including breast cancer." (PMID 31362447, 2019). "In breast cancer, TRPM8 promotes the aggressiveness of breast cancer cells by regulating epithelial-mesenchymal transition (EMT) via the activation of the AKT/GSK-3β pathway." (PMID 29772843, 2018). "Finally, we found that MK2206 also reversed the effect of IQUB overexpression on breast cancer cells by clone formation assay and Wound healing assay, which indicated that IQUB could promote proliferation and migration of breast cancer cells through activating Akt/GSK3β/β‐catenin signaling pathway." (PMID 29968965, 2018). "GSK3B and CTNNB1 are highly expressed in bladder cancer and breast cancer, and they are notably positively correlated." (PMID 30181805, 2018). "Previous studies have confirmed that Akt/GSK-3β modulates the metastasis of different type of tumors by regulating EMT, such as gastric, lung, hepatocellular, breast carcinoma, head and neck squamous cell carcinoma and colorectal, prostate, bladder cancer." (PMID 30670971, 2018). "PIK3CA‐H1047R mammary tumors showed strong activation of phosphorylated AKT, phosphorylated Gsk3‐β, cyclin D1, and activated β‐catenin compared to tumors from Her‐2 transgenic mice." (PMID 28296140, 2017). "In fact, overexpression of either GSK-3α or GSK-3β activates mTORC1 and suppresses autophagy in MCF-7 breast cancer cells." (PMID 29379583, 2017). "THUMPD1 overexpression enhanced breast cancer cells invasion and migration in vivo and in vitro, possibly through activation of AKT, GSK3β and Snail, and inhibition of E-cadherin." (PMID 28076326, 2017). "In the breast cancer core network, we found Fibronectin 1 (FN1), which is related to migration; FLT4 involved in angiogenesis; GSK3B, an anti-proliferative enzyme; KPNA2, a nucleopore transporter and the EP300-associated transcriptional activator NCOA3." (PMID 28775339, 2017). "In our previous study at our laboratory, it was shown that FUT4 and its regulated LeY sugar chains were significantly up-regulated in NSCLC and breast cancer and promoted EMT induction through EGFR and PI3K/Akt-GSK3β activation." (PMID 28423676, 2017). "MCP-1 induces tumorigenesis of breast cancer by stimulating epithelial-mesenchymal transition (EMT) and cell migration, which are mediated by the ERK/GSK-3β/Snail pathway." (PMID 28152041, 2017). "Taken together, our results represent a novel mechanism of GSK-3β, APC, and ICAT downregulation in breast cancer and a functionally and clinically relevant epigenetic mechanism of breast cancer pathogenesis." (PMID 26992223, 2016). "Study also showed that the relevance of GSK‐3β as a target for controlling cell cycle progression and proliferative capacity in MCF7, highlighted the cotreatment of breast cancer." (PMID 27060477, 2016). "Silencing of GSK‐3β by shRNA prevented histone H3 phosphorylation and reduced DNMT1 expression so that can restrain breast cancer cell proliferation." (PMID 27060477, 2016). "The components of the PI3K/Akt and MAPK pathways, including GSK3β, PDK1, and c-RAF have been reported to be involved in breast cancer progression." (PMID 27527857, 2016). "Our study indicated that GSK3β phosphorylates EZH2 at Ser363 and Thr367, resulting in reduced H3K27 trimethylation and biological activity of EZH2 in breast cancer." (PMID 27494834, 2016). "Consistent with the tumor-suppressive effects of GSK-3β, APC, and ICAT, miR-1229 was upregulated in breast cancer, and its overexpression dramatically promoted breast cancer cell proliferation both in vitro and in vivo." (PMID 26992223, 2016). "The correlation between miR-3646 and GSK-3β suggests that GSK-3β is a potential target of miR-3646, which negatively regulates Doc resistance of breast cancer cells." (PMID 27045586, 2016).
breast cancer (continued). "Axin1, recently determined to be a critical protein that is downregulated in breast cancer, targets β-catenin for degradation when complexed with APC, GSK-3β, and CKII." (PMID 26908451, 2016). "Consistent with these notions, NOP14 increased APC and β-catenin levels, as well as GSK-3β phosphorylation level in breast cancer cells; furthermore, NOP14 inhibited the entry of β-catenin into the nucleus of breast cancer cells." (PMID 26213846, 2015). "Data from our previous studies showed that PITPNM3 is a putative receptor for CCL18 on the surface of breast cancer cells and that it mediates the effects of CCL18 by activating both the ERK and Akt/GSK-3β signaling pathways in cancer cells." (PMID 26416449, 2015). "In breast cancer cells, silencing SAM68 resulted in anti-proliferative effects that appeared to be due to up-regulation of p21 and p27 and attenuation of Akt/GSK-3β signaling." (PMID 25944080, 2015). "Filtering specifically for breast cancer datasets that included the recurrence risk during the first year following treatment, we found significant correlations between recurrence and the expression of negative (GSK3β) or positive (TCF4) regulators of Wnt/β-catenin signaling." (PMID 26202299, 2015). "In this study, we further verified ophiobolin O-induced G1 phase arrest in human breast cancer MCF-7 cells, and found that ophiobolin O reduced the phosphorylation level of AKT and GSK3β, and induced down-regulation of cyclin D1." (PMID 25603341, 2015). "These include p190RhoGAP, Rho, RAS, Rac1, Paxillin, p38MAPK, and ERK5 in breast cancer, and AKT, GSK3β, and βCatenin in esophageal cancer." (PMID 24788754, 2014). "Our previous study demonstrated that Bmi-1 promotes the invasion and metastasis of human breast cancer and predicts poor survival, the inhibition of Bmi-1 reverses the expression of EMT markers and inhibits the Akt/GSK3β/Snail pathway." (PMID 22209830, 2012). "Treatment of the MDA-MB-231 breast cancer cell line with APN resulted in the phosphorylation of Akt and in the deactivation of GSK-3β, which subsequently decreased β-catenin expression as well as the transcriptional target of β-catenin, cyclin D1." (PMID 23691481, 2012). "Taken together, we speculate that E-cadherin, Slug and GSK3β could be exploited as markers and pharmacologic or antibody-based therapies targeting the Wnt pathway components, which may not only improve the management of breast cancer, but also affect tumor recurrence and/or metastasis." (PMID 19751508, 2009). "While GSK3β has been shown to mediate apoptosis in several cell types, its role in mediating cytotoxicity in MCF-7 breast cancer cells has only been recently demonstrated." (PMID 17018141, 2006). "Furthermore, GSK-3β can influence cancer cell apoptosis, as demonstrated in MCF7 breast cancer cells where trichostatin A, a histone deacetylase inhibitor (HDACI), induces apoptosis through GSK-3β activation." (PMID 40643495, 2025). "In breast cancer, Notch1 enhances cancer cell proliferation and sustains cancer stem cell activity, whereas Notch3 suppresses epithelial-mesenchymal transition (EMT) by activating glycogen synthase kinase 3 beta (GSK3β) expression." (PMID 41050674, 2025). "We observed a similar effect by pharmacological GSK3B inhibition using SB216763 on PARPi sensitization in murine breast cancer cell 4T1 regardless of BRCA1 status and BRCA1-proficient human breast cancer cells MCF7." (PMID 41243969, 2025). "This reciprocal feedback may also apply to breast cancer, where PAX7 can regulate components of the Wnt/β‐catenin pathway, such as β‐catenin, Wnt ligands, or inhibitors such as GSK3β, while modulating chromatin accessibility or recruiting coregulators." (PMID 40370330, 2025).
breast cancer (continued). "In breast cancer tissues and cells, HDAC8 expression is up‐regulated, and HDAC8 interacts with AKT1, deacetylating it at lysine 426 and activating AKT1, thereby increasing GSK‐3β phosphorylation and promoting its degradation, which triggers the spread and EMT of breast cancer cells." (PMID 39778006, 2025). "Additionally, Shp2 has been found to enhance the proliferation of breast cancer cells by regulating Cyclin D1 stability through the PI3K/Akt and GSK3β pathway." (PMID 39117618, 2024). "Furthermore, EGCG exhibited inhibitory effects on glycogen synthase kinase-3β (GSK-3β) phosphorylation while promoting GSK-3β expression and reducing β-catenin levels in CRC and breast cancer cell lines." (PMID 39690423, 2024). "Apart from melanoma, curcumin effectively modulates the WNT/β-catenin pathway in breast cancer, as it inhibited proliferation and induced the apoptosis of breast cancer cells through the inhibition of DVL, β-catenin and cyclin D1, as well as through the downregulation of phospho-GSK3β and β-catenin." (PMID 39684513, 2024). "Also, p70S6K can phosphorylate and inactivate GSK-3β, which, in turn, is responsible for p70S6K activation, and GSK-3β is considered a key regulatory molecule in the sensitivity of breast cancer cells to chemo-, hormonal, and targeted therapy." (PMID 38786044, 2024). "Finally, a recent study in human breast cancer cells has shown that mortalin supports breast cancer stem cells and enhances EMT through activation of the Wnt/GSK3β/β-catenin signaling pathway." (PMID 36819105, 2023). "This relates to PTEN because GSK3β can mediate the phosphorylation of AKT and PTEN to promote cell migration and apoptosis, which may promote chemoresistance in breast cancer." (PMID 37205308, 2023). "For instance, cophosphorylation of Serum/glucocorticoid-regulated kinase 3 (SGK3) with GSK-3β enhances the binding of FBXW7 to metastasis suppressor N-Myc downstream regulated gene 1 (NDRG1) and promotes NDRG1's ubiquitination, increasing breast cancer invasion and metastasis." (PMID 37658431, 2023). "Phosphorylation of GSK-3β (Ser9) was promoted by activated PRKDC/AKT signaling, while the expression of SNAIL was increased and E-cadherin was decreased in NTF4 over-expressing breast cancer cells." (PMID 36632451, 2023). "A recent study showed that ecto-5′-nucleotidase (CD73) could promote the proliferation of breast cancer cells and breast cells in vitro through the AKT/glycogen synthase kinase-3β (GSK-3β)/β-catenin/cyclin D1 signaling pathway." (PMID 35910774, 2022). "The ERα antagonist MPP inhibits NRF2 activity in MCF-7 breast cancer cells, and oestrogen increases NRF2 activity in MCF7 breast cancer cells by activating the phosphoinositide 3-kinase/glycogen synthase kinase 3 beta (PI3K/GSK3β) pathway." (PMID 36376959, 2022). "In MCF-7 breast cancer cells, silencing the PADI4 gene led to a significant decrease in the nuclear GSK3β level, activation of TGF-β signaling, and induction of the EMT by decreasing E-cadherin and increasing vimentin expression, resulting in more aggressive tumor cells." (PMID 36365233, 2022). "It has been previously reported that CDK1 promotes the migration and metastasis of cancer cells, e.g., colorectal carcinoma and breast cancer cells, by phosphorylating proteins such as EZH2 and activating pathways such as the Wnt/β-Catenin and ERK/GSK3β/SNAI axes." (PMID 35806389, 2022). "To ascertain whether GSK-3β may play different roles in various cancer types, we examined the effects of WT-GSK-3β, KD-GSK-3β, and pLXSN on the therapeutic sensitivity of MCF-7 breast cancer cells." (PMID 33917370, 2021). "Rebeca Santaolalla in a study on the breast cancer cells also showed that TLR-4 enhances migration of breast cancer cells, via PI3K/AKT/GSK3β, and promotes transcription of downstream-catenin target genes (MMP7, MMP9, and VEGFA), leading to breast cancer metastasis." (PMID 34904014, 2021).
breast cancer (continued). "It induces G1 phase arrest in human breast cancer when tested on the Michigan cancer foundation (MCF)-7 cells and reduces the phosphorylation level of protein kinase B (AKT) and Glycogen synthase kinase-3β (GSK3β)." (PMID 34885716, 2021). "However, the PI3K inhibitor reversed the expression levels of EMT markers and modulated the activation of PI3K/AKT/GSK3β pathway, demonstrating that inhibitors targeted PPA1 mediated signaling pathways suppressed breast cancer progression." (PMID 34595179, 2021). "Fucoidan treatment either in vivo (in DMBA-induced mammary cancer in rats, at 200 and 400 mg/kg, by oral route, for 16 weeks) or in vitro (in MDA-MB-231 cells, at 6.25–25 mg/mL) decreased the levels of p-PI3K, p-AKT, and p-GSK-3b (Ser9)." (PMID 34200897, 2021). "In summary, the involvement of a PI3K/Akt/GSK-3β pathway and TRPV6/p85 interaction in breast cancer cell progression revealed in the present study not only confirms the previously reported role of Ca, but more importantly, provides a mechanistic understanding of the disease development." (PMID 34413465, 2021). "Moreover, as was demonstrated in in vivo metastatic breast cancer xenograft model, fisetin reduced lung metastasis and modulated the changes in the expression of EMT molecules and PTEN/Akt/GSK-3β in a similar way as in the in vitro model." (PMID 32521759, 2020). "Estrogen (E2) increases Nrf2 activity in MCF7 breast cancer cells through activation of the PI3K/GSK3β non-genomic pathway." (PMID 32967621, 2020). "While exposing these mesenchyme-like breast cancer cells to GSK3β inhibitors increased CD24 expression, we did not see any change in the CD44 expression." (PMID 30845991, 2019). "Besides, GSK3-β inhibitors 9-ING-41 and 9-ING-87, can suppress the growth of breast cancer cells in vitro and in vivo, and can also sensitize breast cancer patient-derived tumour xenografts to a chemotherapeutic agent irinotecan." (PMID 31362447, 2019). "TP53INP1 inhibits hypoxia‐induced EMT and VM formation via the ROS/GSK‐3β/Snail pathway in breast cancer, especially in triple‐negative breast cancer." (PMID 29655255, 2018). "Therefore, TP53INP1 can be reasonably assumed to suppress hypoxia‐induced breast cancer EMT and VM formation via the GSK‐3β/Snail pathway." (PMID 29655255, 2018). "In conclusion, here we have shown that CPX induced Cdc25A degradation neither by increasing CK1α or decreasing DUB3 expression, nor via activating GSK3β in rhabdomyosarcoma (Rh30) and breast carcinoma (MDA-MB-231) cells." (PMID 29725502, 2018). "Here, we show that CPX induced the degradation of Cdc25A neither by increasing CK1α or decreasing DUB3 expression, nor via activating GSK3β, but through activating Chk1 in rhabdomyosarcoma (Rh30) and breast carcinoma (MDA-MB-231) cells." (PMID 29725502, 2018). "It is thus tempting to speculate that PKD/PKCμ contributes, together down-regulation of GSK3β and up-regulation of p42/p44-MAPK to the MDR-phenotype in breast cancer, concomitantly driving MMP-9 overexpression and thus metastasis." (PMID 29383118, 2017). "It is documented that melatonin activates GSK3β by interfering with Akt phosphorylation to promote β-catenin breakdown and impede the EMT in a xenograft model of breast cancer metastasis, suggesting a circadian control of EMT in the spread of malignancies via regulation of GSK3β." (PMID 28420185, 2017). "Collectively, our data identified a tumor inducer, SYNJ2BP, which could activate the PI3K/AKT/GSK3β/SNAI1 signaling pathway through the lysosome-mediated degradation of PTEN, and promote both EMT and tumor metastasis during the progression of breast cancer." (PMID 29163781, 2017). "We reviewed the functional properties of the driver nodes found to have the highest impact in controlling the essential proteins; they are ERBB2, SRC, PDPK1, PRKDC, mTOR for breast cancer, ERBB2, AKT1, GSK3B, ABL1 in pancreatic cancer, and RET in ovarian cancer." (PMID 28871116, 2017).
breast cancer (continued). "C14orf166 interacts with ninein to block the phosphorylation of ninein catalyzed by GSK-3β, suggesting C14orf166 may inhibit ninein, and activate JAK2 to promote breast cancer progression, but this speculation remain to be confirmation." (PMID 26883017, 2016). "Altogether, our data suggests that stimulation of the hERG1 channel in breast cancer cells activates ubiquitin-proteasome-dependent degradation of cyclin E2 that is independent of GSK3-β." (PMID 25596745, 2015). "Since increased proliferation could be attributed to the activation of cell survival kinases, we compared the phosphorylated and total levels of survival kinases such as AKT, p44/42, p65 and GSK3β in HMEC and breast cancer spheres." (PMID 26608463, 2015). "Elevated basal, ligand-independent, Wnt signaling in some canine breast cancer cells is not caused by classical mutations in APC, β-Catenin or GSK3β but, at least partially, by enhanced LEF1 expression." (PMID 26205886, 2015). "Furthermore, activation of the PI3K/AKT pathway phosphorylates and inactivates GSK3β, suppressing GSK3β-mediated negative regulation of another EMT factor, SNAIL in breast cancer cells." (PMID 26204939, 2015). "In conclusion, our data demonstrated that BrMC may inhibit cell proliferation by suppressing GSK-3β and the β-catenin pathway in HER-2/neu-overexpressing breast cancer cells." (PMID 24765191, 2014). "In conclusion, our data demonstrated that AC may inhibit cell proliferation and the induction of cell death by suppressing GSK-3β and the β-catenin pathway in HER-2/neu-overexpressing breast cancer cells." (PMID 22701509, 2012). "In our previous study, we showed that Bmi-1 could enhance the invasion and metastasis of human breast cancer and predicts poor survival, Bmi-1 silencing reverses the expression of EMT markers and inhibits the Akt/GSK3β/Snail pathway." (PMID 22209830, 2012). "Furthermore, Bmi-1 plays a crucial role in invasion and metastasis by modulating the Akt/GSK-3β/Snail pathway and the expression of EMT markers in breast cancer." (PMID 21276221, 2011). "In this study we use breast cancer cells with low levels of endogenous activated GSK-3 and β-catenin and prostate cancer cells with constitutively activated GSK-3 and β-catenin to show that, GSK3β regulates cadherin-11 expression in two ways." (PMID 19274078, 2009). "The profound increase in P-GSK3 β was more detected in resistant variants of both cell lines, which is in line with a previous study that showed blocking GSK-3β activity may lead to drug and hormonal resistance and modify sensitivity to targeted therapy in MCF-7 breast cancer cells." (PMID 39576770, 2024). "We examined this issue by reducing the prevalence of breast cancer samples (i.e., we only used a half number of breast cancer patients, including 606/1212 randomly selected patients), and we identified a new signature including 7 genes CDK1, AP1S1, CASP3, MAP1LC3A, SNCA, MAPT, and GSK3B." (PMID 38642129, 2024). "In BRCA1 mutant breast cancer overactive Pi3K/AKT signalling in releases GSK3β mediated suppression of NRF2 nuclear translocation, supporting tumour survival, while in colorectal cancer, the regulation of GSK3β activity by the NUAK1/MYPT/PP1 complex maintains nuclear localisation of nuclear NRF2." (PMID 38434478, 2024). "However, we did not identify any interaction between RACK1 and β-catenin or GSK3β in breast cancer cells." (PMID 37848434, 2023). "Notably, high mRNA expression of both Notch3 and GSK3β predicted greater relapse-free survival in overall (p = 1.8 × 10−5) and luminal A breast cancer patients (p = 0.0082), but not luminal B, basal-like or Her 2 subtypes." (PMID 36139447, 2022). "In addition, previous work by our group has demonstrated that increased intracellular zinc release in breast cancer cells by active ZIP7, can also lead to decreased glycogen synthase kinase-3β (GSK3β) through inhibitory phosphorylation, further amplifying AKT driven cell survival." (PMID 35591900, 2022).